PLEKHH3 (pleckstrin homology, MyTH4 and FERM domain containing H3)
Synonyms: FLJ21019
Tractability: Antibody: UniProt predicts a signal peptide or a membrane-spanning region. PROTAC: ubiquitination databases record sites on it.
Gene: Protein-coding gene on chromosome 17 (42,667,914 to 42,677,030, reverse strand). Ensembl gene ENSG00000068137.
Subcellular location (Human Protein Atlas): Golgi apparatus
Gene Ontology:
Cellular component: extracellular region; cytoskeleton
Genetic constraint (gnomAD): Loss-of-function variants: 57 observed, 65.67 expected, observed/expected ratio (o/e) 0.87, 90% interval 0.7 to 1.08. The upper end of that interval is the gene's LOEUF score, 1.08, which puts it in group 4 of 6, group 1 being the genes least tolerant of losing a copy. Missense variants: 1,082 observed, 955.11 expected, observed/expected ratio (o/e) 1.13, 90% interval 1.08 to 1.19. Synonymous variants: 467 observed, 438.33 expected, observed/expected ratio (o/e) 1.07, 90% interval 0.99 to 1.15.
Homologues: Orthologues: chimpanzee PLEKHH3 (99% identical), macaque PLEKHH3 (99% identical), dog PLEKHH3 (96% identical), pig PLEKHH3 (95% identical), mouse Plekhh3 (93% identical), rat Plekhh3 (92% identical), guinea pig PLEKHH3 (82% identical), rabbit PLEKHH3 (82% identical), zebrafish PLEKHH3 (46% identical).
Diseases named in the same sentence as PLEKHH3 in open-access papers:
PLEKHH3 is named in the same sentence as 5 diseases in open-access papers, as found by Europe PMC text mining. Sharing a sentence is not in itself a finding about the gene and the disease. The quoted sentences say what the papers report.
dementia (1 paper, 2024). Loss of intellectual abilities interfering with an individual's social and occupational functions. "Other correlations within the top 10 most significant include PLEKHH3, RGS14, LRCH1, and PCDHB10, notable for their prior implication in dementia and aging." (PMID 38469573, 2024).
endothelial dysfunction (1 paper, 2017). In vascular diseases, endothelial dysfunction is a systemic pathological state of the endothelium (the inner lining of blood vessels) and can be broadly defined as an imbalance between vasodilating and vasoconstricting substances produced by (or acting on) the endothelium. "We think that PLEKHH3, another PH family member, may play a pivotal role in chronic IHR-related endothelial dysfunction in OSA patients through regulating tight junction formation of endothelial cells specifically." (PMID 28520763, 2017).
Hypertension (1 paper, 2017). The presence of chronic increased pressure in the systemic arterial system. "Moreover, we verified AMOT, PLEKHH3, ADAR, BIRC3, and LGALS3 protein over-expressions in the treatment-naïve OSA patients, and discovered a correlation between AMOT/BIRC3/LGALS3 protein expression and the presence of EDS/hypertension/CKD, respectively." (PMID 28520763, 2017).
obstructive sleep apnea (1 paper, 2022). "Overexpression of PLEKHH3 was identified in blood immune cells associated with obstructive sleep apnea, while the role of PLEKHH3 in cancer has not been described until now." (PMID 36230614, 2022).
PLEKHH3 also shares sentences with these, for which no sentence is quoted: cancer (1 paper).